RN7SL25P (RNA, 7SL, cytoplasmic 25, pseudogene)
Gene: Miscellaneous RNA gene on chromosome 9 (6,542,094 to 6,542,353, forward strand). Ensembl gene ENSG00000264530.
Homologues: Paralogues in human: RN7SL474P (79% identical), RN7SL460P (79% identical), RN7SL835P (79% identical), RN7SL784P (78% identical), RN7SL96P (78% identical), RN7SL811P (78% identical), Metazoa_SRP (77% identical), RN7SL134P (77% identical), RN7SL774P (77% identical), RN7SL819P (77% identical), RN7SL163P (77% identical), RN7SL510P (77% identical), and 705 more.